OTUB1 (OTU deubiquitinase, ubiquitin aldehyde binding 1)
Diseases named in the same sentence as OTUB1 in open-access papers (continued):
Sharing a sentence is not in itself a finding about the gene and the disease.
colorectal cancer (21 papers, 2014 to 2025). A primary or metastatic malignant neoplasm that affects the colon or rectum. "We report, for the first time, that curcumol suppresses colorectal cancer progression by downregulating OTUB1 expression, thereby targeting tumor-associated angiogenesis." (PMID 40430059, 2025). "In general, OTUB1 is known to be associated with the development and metastasis of colorectal cancer, ovarian cancer, and lung cancer, and increased OTUB1 expression is associated with worsening prognosis." (PMID 29558500, 2018). "The aim of this study was to clarify the role of OTUB1 in colorectal cancer (CRC) and to identify the mechanism underlying its function." (PMID 25431208, 2014). "Notably, increased OTUB1 expression in colorectal cancer is associated with metastatic potential and unfavorable clinical outcomes." (PMID 40430059, 2025). "Studies have demonstrated that elevated OTUB1 expression in colorectal cancer patients correlates with poor prognosis, increased tumor aggressiveness, and higher recurrence rates." (PMID 40430059, 2025). "Mechanistic studies revealed that curcumol modulates TGFBI ubiquitination by suppressing OTUB1-mediated protein stabilization, ultimately attenuating angiogenesis in colorectal cancer." (PMID 40430059, 2025). "Based on current research evidence, this study elucidates the molecular mechanism by which curcumol suppresses angiogenesis and metastasis in colorectal cancer through modulation of the OTUB1/TGFBI signaling pathway." (PMID 40430059, 2025). "Recent studies showed that OTUB1 is elevated in colorectal cancer, promotes metastasis and serves as a marker of poor prognosis of colorectal cancer." (PMID 39113709, 2024). "For example, OTUB1 promotes colorectal cancer metastasis by promoting EMT and serves as a potential distant metastasis marker in colorectal cancer." (PMID 39484165, 2024). "OTUB1 promotes colorectal cancer metastasis by facilitating EMT and acts as a potential distant metastasis marker and prognostic factor in CRC." (PMID 36369321, 2023). "OTUB1 has been reported to have oncogenic potential in several solid tumors, facilitating epithelial-mesenchymal transition in colorectal cancer cells and glioma cells, and inducing metastatic spread in esophageal squamous cell carcinoma." (PMID 35159073, 2022). "MicroRNA-542-3p can increase OTUB1 mRNA and protein levels to inhibit the proliferation, migration, and invasion of colorectal cancer cells." (PMID 34778410, 2021). "ERK can directly bind to the promoter region of OTUB1 to regulate its expression in colorectal cancer." (PMID 34778410, 2021). "In this study, we found that estrogen-related receptor alpha (ERRα, also called NR3B1) binds to OTUB1 promoter and regulates its expression in colorectal cancer." (PMID 31737118, 2019). "In conclusion, our study provides the first elucidation of the molecular mechanism by which curcumol suppresses colorectal cancer angiogenesis through downregulating OTUB1 expression, thereby blocking its deubiquitinating effect on TGFBI and promoting TGFBI ubiquitination-mediated degradation." (PMID 40430059, 2025). "The relationship between OTUB1 and the wnt/β-catenin signaling pathway remains unclear, previous studies indicated that OTUB1 binds with β-catenin and regulates its degradation in colorectal cancer." (PMID 39113709, 2024). "Yuan et al49 showed that miR‐542‐3p expression was downregulated in colorectal cancer tissues and cells and that miR‐542‐3p overexpression inhibited cell proliferation, migration, and invasion and promoted cell apoptosis through targeted binding to OTUB1." (PMID 32167655, 2020). "For example, OTUB1 is found to be up-regulated in colorectal cancer, gastric adenocarcinoma, esophageal cancer, ovarian cancer, human glioma, and hepatocellular carcinoma, which could promote tumor invasion and predict a poor prognosis." (PMID 33537306, 2020). "MiR-542-3p functioned as a tumor repressor in colorectal cancer by targetting OTUB1." (PMID 30042169, 2018).
colorectal cancer (continued). "There may be a variety of mechanisms involved in OTUB1 promoting the metastasis of colorectal cancer." (PMID 25431208, 2014). "Therefore, OTUB1 represents a potential biomarker for evaluating colorectal cancer progression and predicting patient outcomes.Theinhibition of OTUB1 activity or the downregulation of its expression may contribute to controlling colorectal cancer progression." (PMID 40430059, 2025). "Based on these findings of previous studies, OTUB1 promotes the metastasis of esophageal squamous cell carcinoma by modulating snail stability, while different expression of OTUB1 affects the migration and progression of colorectal cancer through the regulation of ERRα or mir-542-3p." (PMID 33537306, 2020). "Our findings elucidate the molecular mechanism by which curcumol exerts its anti-metastatic effects through the regulation of the OTUB1/TGFBI axis, highlighting its potential as a novel therapeutic agent for colorectal cancer treatment." (PMID 40430059, 2025). "SLC7A11 attracted our attention as it is identified as the substrate of OTUB1 in other tumors and targeting SLC7A11 indeed can specifically kill CSCs in colorectal cancer." (PMID 34927544, 2021).
ovarian tumor (20 papers, 2014 to 2025). "OTUB1 is characterized by an ovarian tumor (OTU) domain and encodes a protein that is a specific ubiquitin iso‐peptidase that cleaves ubiquitin from branched poly‐ubiquitin chains." (PMID 38069522, 2023). "In the same way, Otubain 1 (OTUB1) is a deubiquitinase member of the ovarian tumor (OTU) domain family that specifically cleaves K48-linked polyubiquitin chains, regulates many cancer associated signaling pathways, and has a critical role in cancer initiation and progression." (PMID 33800394, 2021). "Otubain-1 (OTUB1) belongs to the deubiquitinating enzyme family called ovarian tumor (OTU) domain cysteine protease superfamily and is capable of specifically removing Lys48-linked ubiquitin chains from its substrate." (PMID 36831318, 2023). "OTUB1 is an ovarian tumor deubiquitinase family member with reported functions to regulate SLC7A11 stability via direct protein interaction." (PMID 35347117, 2022). "Otubain 1 (OTUB1) belongs to a family of deubiquitinases (DUBs), for which their defining feature is their ovarian tumor (OTU) domain, and OTUB1 promotes aggressive behavior in several cancers through both canonical and non-canonical DUB functions." (PMID 34205406, 2021). "OTUB1 (ovarian tumor domain protease domain-containing ubiquitin aldehyde-binding proteins)-mediated deubiquitination of FOXM1 (Forkhead box M1) participates in carcinogenesis of various tumors." (PMID 32257108, 2020). "TRAF3 poly-ubiquitylation is downregulated by a deubiquitylating enzyme otubain 1 (OTUB1) which belongs to the ovarian tumor (OTU) family of cysteine proteases." (PMID 32586037, 2020). "Thus, Pearson correlation analysis between the expression level of B4GALT5 and OTU (ovarian tumour) family deubiquitinases (OTUB1, OTUB2, OTUD1, YOD1, OTUD3, OTUD4, OTUD7B) was performed." (PMID 36611197, 2023). "OTUB1 was previously identified as a member of the ovarian tumor domain containing a superfamily of proteases that has two distinct activities: canonical enzymatic activity for K48-linked polyubiquitin hydrolysis and non-canonical activity for the formation of E2-repressive complex." (PMID 35732631, 2022). "Ovarian tumor (OTU)-containing DUBs is one of the members of DUBs and OTUB1 (ovarian tumor domain protease domain-containing ubiquitin aldehyde-binding proteins) is a member of OTU domain protease superfamily of DUBs that removes ubiquitin from branched polyubiquitin chains in the target molecules." (PMID 32257108, 2020). "In the screening experiment, we found that overexpression of OTUB1, a DUB of the ovarian tumour proteases (OTU) subfamily, markedly increased the protein abundance of CCN6 in 4T1 cells." (PMID 37608493, 2023). "Many other de-ubiquitinases (DUBs), including USP14 and Ovarian Tumor (OTU, Ubiquitin Aldehyde Binding-1) OTUB-1 regulate tau (de)ubiquitination and control its proteasome clearance." (PMID 34564439, 2021). "OTUB1 (OTU deubiquitinase, ubiquitin aldehyde binding 1) is a deubiquitinating enzyme (DUB) that belongs to the OTU (ovarian tumor) superfamily." (PMID 25431208, 2014). "In addition, OTUB1 (OTU deubiquitinase, ubiquitin aldehyde binding 1) is an ovarian tumor (OTU) family member deubiquitinase." (PMID 32103754, 2020).
gastric cancer (18 papers, 2018 to 2025). A primary or metastatic malignant neoplasm involving the stomach. "The clinical data analysis implicated OTUB1 was higher expressed in gastric cancer, which correlated with YAP activity and poor survival." (PMID 36271031, 2022). "In gastric cancer, OTUB1 is an independent risk factor for disease-specific survival and enhances tumor invasiveness." (PMID 31737118, 2019). "The endogenous immuno-precipitation assay indicated that OTUB1 could associate with YAP in gastric cancer cells." (PMID 36271031, 2022). "As a result, OTUB1 promotes gastric cancer cell proliferation, migration, and invasion as well as stemness through YAP1." (PMID 38264570, 2023). "The authors showed OTUB1 inhibits ferroptosis in gastric cancer and promotes cell proliferation as well as migration and invasion." (PMID 38264570, 2023). "We demonstrated that CST1 relieves the ubiquitination of GPX4 through OTUB1, thereby promoting ferroptosis resistance in gastric cancer cells." (PMID 36369321, 2023). "For example, OTUB1 can promote the progression, metastasis and invasion of gastric cancer (GC), prostate cancer and colon cancer." (PMID 37251574, 2023). "We discovered OTUB1 as a critical factor to facilitate gastric cancer cell stemness and progression, which deubiquitinated and stabilized YAP protein." (PMID 36271031, 2022). "In conclusion, we discovered the novel regulation link between Hippo/YAP axis and OTUB1 in gastric cancer." (PMID 36271031, 2022). "The protein half-life assay showed that OTUB1 depletion impaired the YAP protein stability in gastric cancer cells." (PMID 36271031, 2022). "Our clinical sample and biological studies showed that OTUB1 was an oncogene in supporting gastric cancer proliferation and metastasis in vitro and in vivo." (PMID 36271031, 2022). "We further analyzed the expression of OTUB1 in gastric cancer, while the TCGA database showed that OTUB1 was higher expression in gastric cancer compared with normal gastric tissues." (PMID 36271031, 2022). "In our study, our siRNA screening data indicated the critical role of OTUB1 in Hippo signaling in gastric cancer." (PMID 36271031, 2022). "In gastric cancer, although there was report showing OTUB1 was higher expression in gastric malignancies compared with normal tissue, the detailed mechanism was not clear." (PMID 36271031, 2022). "Further analysis revealed that OTUB1 was elevated in all stages of gastric cancer compared with normal gastric tissue." (PMID 36271031, 2022). "CST1 promotes gastric cancer metastasis by regulating GPX4 protein stability via OTUB1." (PMID 39605891, 2024). "In vitro study showed OTUB1 promotes gastric cancer cell migration and invasion." (PMID 38264570, 2023). "Two later studies provided mechanistic insight into the function of OTUB1 in gastric cancer." (PMID 38264570, 2023). "We further depleted OTUB1 in AGS gastric cancer cells for RNA sequence analysis." (PMID 36271031, 2022). "We further explored the effect of OTUB1 in gastric cancer phenotypes." (PMID 36271031, 2022). "The CCK-8 assay and EdU staining assay showed that OTUB1 depletion inhibited gastric cancer growth, while YAP over-expression could partially rescue such growth inhibition." (PMID 36271031, 2022). "The CCK-8 assay showed that OTUB1 overexpression promoted gastric cancer growth, while YAP knockdown could rescue such growth promotion." (PMID 36271031, 2022). "In addition, WGCNA analysis based on the expression prolife of GSE29272 indicated that OTUB1 was positively correlated with genes belongs to the grey module in gastric cancer." (PMID 36271031, 2022). "We further analyzed the expression of YAP and OTUB1 in gastric cancer samples." (PMID 36271031, 2022). "Taking together, we propose that OTUB1 could a positive regulator for Hippo/YAP signaling in gastric cancer." (PMID 36271031, 2022). "Interestingly, our screening data indicated OTUB1 was a novel deubiquitinase in modulating Hippo signaling function in gastric cancer." (PMID 36271031, 2022).
gastric cancer (continued). "Combined with the other oncogenic role of OTUB1 in previous studies, blocking OTUB1 could result in the inhibition of multiple oncogenic pathways and synchronize in gastric cancer therapy." (PMID 36271031, 2022). "OTUB1 supported gastric cancer proliferation and metastasis via enhancing Hippo/YAP axis activity." (PMID 36271031, 2022). "All these data indicate OTUB1 plays important roles in facilitating gastric cancer progression." (PMID 36271031, 2022). "The CCK-8 assay showed that OTUB1 depletion inhibited gastric cancer growth, while YAP-S5A over-expression could totally rescue such growth inhibition." (PMID 36271031, 2022). "Since OTUB1 has been proved as an important deubiquitinase in Hippo signaling, targeting OTUB1 function or modulating OTUB1 expression could be a plausible strategy for gastric cancer therapeutics." (PMID 36271031, 2022). "In the study, we identified OTUB1 as a critical factor for gastric cancer progression." (PMID 36271031, 2022). "For example, cysteine protease inhibitor SN (CST1) could regulate the protein stability of glutathione peroxidase 4 (GPX4) through OTUB1 and inhibit the ferroptosis of gastric cancer cells, which in turn promoted the metastasis of gastric cancer to the liver, lungs and peritoneum." (PMID 40178680, 2025). "For instance, OTUB1 inhibited ferroptosis by improving GPX4 protein stability and reducing intracellular reactive oxygen species (ROS), which in turn promoted gastric cancer metastasis." (PMID 40469292, 2025). "In gastric cancer, both CST1 and OTUB1 are involved in the development and progression of the disease." (PMID 40387552, 2025). "CST1 relieves GPX4 ubiquitination modification by recruiting OTUB1, improving GPX4 protein stability and reducing intracellular reactive oxygen species (ROS), thereby inhibiting ferroptosis and, in turn, promoting gastric cancer metastasis." (PMID 36369321, 2023). "In the KMPLOT analysis, we found that both OTUB1 and YAP expression related to poor survival in gastric cancer patients." (PMID 36271031, 2022). "Since OTUB1 modulates Hippo/YAP axis and gastric cancer progression, we further investigated the potential mechanism." (PMID 36271031, 2022). "Our DUBs siRNA screening data not only provided an overall picture of DUBs effects on Hippo signaling, but also identified OTUB1 as a critical deubiquitinase in modulating YAP stability and gastric cancer progression." (PMID 36271031, 2022). "In gastric cancer (GC), DUBs like USP20, OTUB1, and OTUD1 play significant roles." (PMID 39678489, 2024). "Similar to our results, a previous study reported that OTUB1 interacted with CST1 and enhanced the protein stability of GPX4, thereby reducing the ubiquitination of GPX4, inhibiting ferroptosis, and promoting the metastasis and progression of gastric cancer." (PMID 39500879, 2024). "Furthermore, our previous studies verified that OTUB1 and DUB1 promote gastric cancer cell progression and invasion by positively regulating Hippo signaling." (PMID 37041150, 2023). "Mechanistically, CST1 relieves GPX4 ubiquitination by recruiting the deubiquitinating enzyme OTUB1, improving GPX4 protein stability and reducing intracellular reactive oxygen species ROS, thereby inhibiting ferroptosis and, in turn, promoting EMT and metastasis of gastric cancer cells." (PMID 36369321, 2023). "Although YAP1 has already been identified as a substrate of OTUB1 in the regulation of stemness and progression of gastric cancer cells, there have been no reports on the regulation of YAP1 by OTUB1 in HNSCC to date." (PMID 37986681, 2023). "Our study proposed a non-genomic regulation between OTUB1 and Hippo/YAP axis and a promising target for gastric cancer treatments." (PMID 36271031, 2022).
lung carcinoma (16 papers, 2016 to 2025). "Ubiquitin thioesterase OTUB1 regulates multiple pathways in cancer progression and increased expression of OTUB1 is associated with poor prognosis in several cancers including lung cancer." (PMID 31231223, 2019). "In lung cancer, for example, OTUB1 stabilized the CHK1 protein through deubiquitination, enhancing the cell’s ability to repair DNA and aiding cancer cell survival." (PMID 40469292, 2025). "In lung cancer, OTUB1 triggered lung cancer development by inhibiting RAS monoubiquitination; OTUB2 stabilized U2AF2 through the AKT/mTOR signaling pathway to promote the Warburg effect and tumorigenesis; and OTUD3 stabilized GRP78 to augment the malignancy." (PMID 40469292, 2025). "OTUB1 gene amplification in lung cancer is exclusive with RAS activating mutation, indicating OTUB1 is a driving force for the activation of wildtype RAS." (PMID 38264570, 2023). "In contrast, OTUB1 knockdown decreases oxidative phosphorylation of lung cancer cells and inhibits cell proliferation." (PMID 38264570, 2023). "OTUB1 knockout lung cancer cells proliferate much slower under hypoxia than control cells with decreased glycolysis and glucose uptake." (PMID 38264570, 2023). "Instead, they found hypoxia changes the interactome of OTUB1 protein in A549 lung cancer cells, reminiscent of a previous report." (PMID 38264570, 2023). "Recent studies have reported the oncogenic role OTUB1 in many cancers, such as prostate, ovarian, breast and lung cancer, esophageal squamous cell carcinoma (ESCC), hepatocellular carcinoma (HCC), and CRC." (PMID 31737118, 2019). "To confirm the contribution of OTUB1 to lung cancer development, we performed immunohistochemistry analysis of a NSCLC tissue array." (PMID 26881969, 2016). "Specifically, we found that the de‐ubiquitinase OTUB1 promotes lung cancer formation and correlates with poorer patient prognosis." (PMID 26881969, 2016). "Notably, our clinical analysis revealed that OTUB1 was the second DUB candidate associated with a high stemness index score and poor outcome in lung cancer patients." (PMID 37726816, 2023). "Similar results were also observed in siRNA-mediated knockdown of cathepsin K. Cathepsin K siRNA decreased Raptor protein expression and phosphorylation of OTUB1 and Src in Caki-1 (renal carcinoma), A549 (lung carcinoma), and DU145 (prostate carcinoma) cells, significantly." (PMID 37330581, 2023). "Functionally, OTUB1 promotes the oxidative phosphorylation of lung cancer cells." (PMID 38264570, 2023). "Consistently, RAS-wildtype lung cancer cells tend to be more dependent on OTUB1." (PMID 38264570, 2023). "However, in another published cohort of 1926 cases of lung cancer, OTUB1 mRNA expression level was a significant poor prognostic marker (P=0.0025 for overall survival, Kaplan–Meier analysis)." (PMID 26148240, 2016). "Our study identifies OTUB1 as a key player in the pathogenesis of wt KRAS lung cancers." (PMID 26881969, 2016). "In addition, OTUB1 could facilitate lung cancer formation via stabilizing RAS signaling." (PMID 36271031, 2022). "In addition, OTUB1 can inhibit the monoubiquitylation of RAS, promote lung cancer progression, stabilize Snail protein levels, and promote the metastasis of esophageal squamous carcinoma." (PMID 35494004, 2022). "Moreover, in lung cancer, by inhibiting RAS ubiquitination, OTUB1 triggers cancer development." (PMID 31737118, 2019).